RN7SL634P (RNA, 7SL, cytoplasmic 634, pseudogene)
Gene: Miscellaneous RNA gene on chromosome 14 (104,013,642 to 104,013,933, forward strand). Ensembl gene ENSG00000242894.
Homologues: Orthologues: chimpanzee Metazoa_SRP (97% identical), macaque Metazoa_SRP (90% identical). Paralogues in human: RN7SL3 (80% identical), RN7SL1 (80% identical), RN7SL2 (79% identical), RN7SL126P (78% identical), RN7SL543P (78% identical), RN7SL630P (78% identical), RN7SL546P (77% identical), RN7SL664P (77% identical), RN7SL679P (77% identical), RN7SL14P (77% identical), RN7SL408P (77% identical), RN7SL481P (77% identical), and 700 more.